SLC2A2 (solute carrier family 2 member 2)
Diseases named in the same sentence as SLC2A2 in open-access papers (continued):
Sharing a sentence is not in itself a finding about the gene and the disease.
Hypoglycemia (35 papers, 2011 to 2025). A decreased concentration of glucose in the blood. "Patients harbouring mutations in the SLC2A2 gene (Fanconi–Bickel disease) suffer fasting hypoglycaemia and liver glycogen accumulation, indicating that GLUT2 is required for glucose to leave the hepatocyte." (PMID 27707936, 2016). "It is reported pantothenic acid appears to be part of a glucose carrier system, therefore, PAD may direct reduce SLC2A2 and resulted in abnormal glucose absorption and hypoglycemia in ducks." (PMID 34193047, 2021). "Decreased protein expression of SLC2A2, VIL1, and EZR due to PAD probably impair glucose absorption system, which may provide a possible explanation for fasting hypoglycemia that is seen." (PMID 34193047, 2021). "However, the exact mechanism by which ADCY7 leads to excessive insulin secretion through GSIS is still not explained by only increasing SLC2A2 and GCK expression during hypoglycemia conditions." (PMID 34177802, 2021).
Fanconi-Bickel syndrome (32 papers, 2010 to 2025). "A homozygous variant of the SLC2A2 gene (Fanconi-Bickel syndrome) was found in one patient (Case 25)." (PMID 36178555, 2023). "Fanconi-Bickel syndrome (also known as GSD type XI) is caused by mutations in the GLUT2 (SLC2A2) gene." (PMID 35422763, 2022). "GSD type XI is caused by defective glucose and galactose transporter GLUT2 (SLC2A2 gene, chromosome 3q26.1–26.3), expressed in hepatocytes, pancreatic β-cells, enterocytes and renal tubular cells." (PMID 35725468, 2022). "Regarding the OB population, it is known that the Fleckvieh haplotype 2 (FH2) and the associated frameshift variant in the SLC2A2 gene segregate in the OB population at an allele frequency of 0.05 and cause the Fanconi-Bickel syndrome with growth retardation." (PMID 34915862, 2021). "Mutations in the human SLC2A2 gene (which encodes for GLUT2 protein) cause Fanconi-Bickel syndrome (hepatomegaly and renal disease) and have been rarely found as a cause of neonatal diabetes." (PMID 32938474, 2020). "Both variants of c.1043dupT and c.613-1G > C in SLC2A2 gene have been associated with Fanconi-Bickel syndrome (GSDXI)." (PMID 33505429, 2020). "Mutations in SLC2A2 in Fleckvieh cattle caused clinical signs characterized by hepatic glycogen accumulation, which is similar to Fanconi-Bickel syndrome observed in humans with SLC2A2 mutations." (PMID 29738450, 2018). "Mutations in human SLC2A2 cause Fanconi-Bickel syndrome (FBS), a rare recessive glycogen storage disorder which results in severe growth retardation." (PMID 25927203, 2015). "Slc2a2 (also known as the glucose transporter gene GLUT2) is a disease causing gene for Fanconi-Bickel syndrome, which has systemic as well as characteristic tubular nephropathy abnormalities." (PMID 22970174, 2012). "Clinical data shows that SLC2A2 (GLUT2) mutations are the cause for Fanconi-Bickel syndrome, a rare autosomal recessive disease about carbohydrate metabolism dysfunction, and the tested patients showed typical characteristics such as glycogen storage disorders and proximal renal tubular nephropathy." (PMID 30956980, 2019). "This hypothesis is supported by clinical evidence showing mutations in SLC2A2 reduce transporter function cause Fanconi-Bickel Syndrome, which leads to an enlarged liver resulting from excessive glycogen accumulation." (PMID 23840313, 2013). "Although the functional consequences of these polymorphisms are unknown, mutations of SLC2A2, which is highly expressed in the liver and the β-cell islets, cause Fanconi-Bickel syndrome." (PMID 23341889, 2013). "Fanconi-Bickel syndrome (FBS, OMIM #227810) is a rare autosomal recessive disorder of carbohydrate metabolism caused by pathogenic variants in the GLUT2 (SLC2A2) gene." (PMID 34828390, 2021). "A frameshift variant in SLC2A2 (NM_001103222:c.771_778delTTGAAAAGinsCATC, rs379675307, OMIA 000366–9913) causes a recessive disorder in cattle that resembles human Fanconi-Bickel syndrome." (PMID 31914939, 2020). "Genetic variants of transporters contributing to intestinal sugar transport are associated with human diseases, such as glucose-galactose malabsorption and Fanconi-Bickel syndrome caused by mutations in SGLT1 (SLC5A1) and GLUT2 (SLC2A2), respectively." (PMID 33015026, 2020). "Fanconi-Bickel syndrome (FBS) is a rare condition of carbohydrate metabolism, caused by a recessive defect in the facilitative glucose transporter GLUT2 encoded by the SLC2A2 gene and characterized by a wide spectrum of phenotypical features." (PMID 33292488, 2020). "The affected calves exhibit stunted growth, resembling the phenotypic appearance of Fanconi-Bickel syndrome in humans (OMIM 227810), which is also caused by mutations in SLC2A2." (PMID 25927203, 2015). "Two genes, HNF4A (Hepatocyte Nuclear Factor 4 Alpha) and SLC2A2 (Solute Carrier Family 2 Member 2) causing renal Fanconi syndrome 4 and Fanconi-Bickel syndrome, respectively, are not yet classified due to the reduced number of cases published so far." (PMID 32150856, 2020).
Fanconi-Bickel syndrome (continued). "This HNF4α mutations might decrease the expression of SLC2A2 in both liver and kidney, and are responsive to diazoxide therapy, unlike the Fanconi-Bickel syndrome." (PMID 35422763, 2022). "Furthermore, specific mutations p.R63W and LRG_483t1:c.427-1G>A in HNF4α cause HI associated to hepatomegaly and renal Fanconi syndrome, a phenotype similar to Fanconi-Bickel syndrome (due to inactivating mutations of SLC2A2 resulting in nonfunctional glucose transporter 2, GLUT2)." (PMID 35422763, 2022).
Obesity (25 papers, 2012 to 2025). Accumulation of substantial excess body fat. "As a result, the expressionof these genes (Slc2a2, Gck, Pklr, G6P, and Pck1) was lowerin females than in males under SFD-induced obesity." (PMID 35087997, 2020).
hepatocellular carcinoma (18 papers, 2014 to 2026). A malignant tumor that arises from hepatocytes. "In hepatocellular carcinoma, the SLC2A2 mRNA and GLUT2 protein expressions were found to be higher than those of other GLUTs and were associated with poor overall patient survival." (PMID 36839686, 2023). "Genes regulating glycogen metabolism (Gys2), glycolysis (Aldob and Eno2) and glucose transport (Slc2a2) were all affected by Tcf7l2 silencing in the hepatoma cells, suggesting that TCF7L2 activity is an important determinant of carbohydrate metabolism overall in the liver." (PMID 25414334, 2014). "Despite its significance, the role of SLC2A2 in liver differentiation and hepatocellular carcinoma (HCC) remains underexplored." (PMID 40279337, 2025).
Glucose intolerance (17 papers, 2008 to 2025). Glucose intolerance (GI) can be defined as dysglycemia that comprises both prediabetes and diabetes. "Interestingly, deletion of the Hif1a gene in β-cells causes impaired insulin secretion and glucose intolerance in mice with a decreased expression of Slc2a2 (encoding GLUT2) and Gck (encoding glucokinase)." (PMID 38673770, 2024).
insulinoma (13 papers, 2008 to 2025). "The expression of SLC2A2 (also known as glucose transporter 2 [GLUT2]) was used to identify insulinoma cells." (PMID 36301668, 2022). "High expression of SLC2A2 expression has also been reported in some human insulinomas." (PMID 40438247, 2025). "The transdifferentiated PANC-1 and MIA PaCa-2 cells expressed 80.63% and 56.1%, respectively, of the INS mRNA levels seen in the insulin-producing human insulinoma cell line NT-3, while the abundance of SLC2A2 and MAFA transcripts was higher and lower, respectively, than in NT-3 cells." (PMID 34572891, 2021). "Menin knockdown concomitantly decreased the mRNA expression of both MAFA and β-cell differentiation markers (INS, GCK, SLC2A2, and PDX1) while increasing tumor proliferation, indicating that altered menin expression disrupts the MAFA differentiation pathway in insulinoma." (PMID 35406570, 2022).
type 1 diabetes (12 papers, 2013 to 2025). "However, the presence of the minor alleles in SLC2A2 rs5400 appeared to increase the risk of type 1 diabetes." (PMID 31728565, 2020). "However, a common variant in the SLC2A2 gene (rs5400) was associated with an increased risk of type 1 diabetes, while a less frequent variant in SLC23A1 (rs33972313) showed an association of borderline statistical significance." (PMID 31728565, 2020). "The SLC2A2 rs5400 SNP was associated with increased risk of type 1 diabetes (OR 1.77 [95% CI 1.12, 2.80]), independent of plasma ascorbic acid (OR 0.92 [95% CI 0.84, 1.00])." (PMID 31728565, 2020). "The SLC2A2 rs5400 SNP did not modify the association of plasma ascorbic acid status with the risk of islet autoimmunity or type 1 diabetes, IAA first or GADA first." (PMID 31728565, 2020).
steatosis (10 papers, 2014 to 2025). Increased lipid within the cytoplasm of cells. "The inability of the FG-4497 treatment to protect against steatosis compared with the Hif-p4h-2gt/gt livers associated with only a few lipogenic mRNAs and Slc2a2 being downregulated, and conversely with Pparg mRNA upregulation." (PMID 32296880, 2020). "Moreover, peroxisome proliferative activated receptor-γ co-activator 1 (PPARγ) expression, a stimulator of endogenous SLC2A2 mRNA transcription and key regulator of the genes associated with steatosis liver, was enhanced by about 40% after the leucine treatment (P ≤0.05)." (PMID 25859286, 2014).
metabolic syndrome (8 papers, 2013 to 2025). A cluster of metabolic risk factors for CARDIOVASCULAR DISEASES and TYPE 2 DIABETES MELLITUS. "In conclusion, this exploratory study detected some potentially interesting associations between polymorphisms of SLC2A2 and SLC2A5 with various aspects of the metabolic syndrome in the study population of PEAR." (PMID 23341889, 2013).
glycogen storage disorder (7 papers, 2015 to 2025). "Also, SLC2A2 showed decreased expression levels; the product of this gene plays an important role in glycogen storage disease." (PMID 27242740, 2016).
liver cancer (7 papers, 2020 to 2026). An epithelial or non-epithelial malignant neoplasm that arises from the liver. "Future studies should focus on unraveling the precise molecular mechanisms of SLC2A2 in hepatocyte differentiation and its potential as a therapeutic target in liver cancer." (PMID 40279337, 2025). "At the protein expression level, using HCC samples and liver cancer samples from the Clinical Proteomic Tumor Analysis Consortium (CPTAC), it was further confirmed that SLC2A2 was lower expressed and TMCC1 was more highly expressed in HCC tissues." (PMID 37409259, 2023). "However, researchers found that although the expression of GLUT2 (SLC2A2) was significantly lower in liver cancer than that of GLUT1, GLUT2 had a more significant prognostic value, with the late clinical staging and overall survival of HCC patients highly dependent on GLUT2 expression." (PMID 40028341, 2025).
hypothyroidism (6 papers, 2015 to 2025). Abnormally low levels of thyroid hormone. "The effect of treatment (hypothyroidism) was significant for Slc27a4, Npc1l1, Slc2a2 and Slc2a5." (PMID 39958687, 2025).
Impaired glucose tolerance (6 papers, 2014 to 2023). An abnormal resistance to glucose, i.e., a reduction in the ability to maintain glucose levels in the blood stream within normal limits following oral or intravenous administration of glucose. "Moreover, pathogenic Slc2a2 variants are also associated with an increased risk for the transition from impaired glucose tolerance to T2D." (PMID 34571259, 2021).
breast carcinoma (5 papers, 2017 to 2024). "However, expression of SLC2A2 was inversely associated with invasiveness in breast cancer." (PMID 28978124, 2017). "According to the results, the mRNA expression of SLC2A1 was significantly higher in breast cancer, while the expression levels of SLC2A2–4 were downregulated." (PMID 34525987, 2021). "In our study, the mRNA expression of SLC2A1 was significantly higher in breast cancer, while the expression levels of SLC2A2–4 were downregulated." (PMID 34525987, 2021). "Conversely, the transcriptional levels of SLC2A2–4 were not significantly upregulated, but showed downregulation in breast cancer." (PMID 34525987, 2021).
galactose intolerance (5 papers, 2016 to 2024). "Furthermore, some mutations in the glucose transporter SLC2A2 can cause neonatal diabetes prior to the Fanconi–Bickel syndrome associated with glycosuria, galactosemia, aminoaciduria, proteinuria, hepatomegaly, as well as glucose and galactose intolerance." (PMID 34079523, 2021).
pancreatic cancer (5 papers, 2012 to 2022). "Hence, SLC2A2 was seemingly the only gene that was expressed significantly higher in liver metastatic lesions in comparison to the primary pancreatic tumors, in both the datasets." (PMID 22412968, 2012). "The comparison revealed that ALDOB, SLC2A2, PC and PCK1 mRNA levels were significantly higher in the liver metastatic lesions in comparison to the primary pancreatic tumors." (PMID 22412968, 2012).
neonatal diabetes mellitus (4 papers, 2016 to 2021). Neonatal diabetes mellitus presents as hyperglycemia, failure to thrive and, in some cases, dehydration and ketoacidosis which may be severe with coma, in a child within the first months of life. "Mutations in the SLC2A2 gene may cause Fanconi–Bickel disease and neonatal diabetes mellitus due to deficient insulin secretion." (PMID 27707936, 2016).
colorectal cancer (3 papers, 2019 to 2023). A primary or metastatic malignant neoplasm that affects the colon or rectum. "Genes SLC2A2, TNC1 and MIR518A2 were reported to be associated with lung cancer, gastric cancer and colorectal cancer, respectively." (PMID 31640538, 2019).
glucosuria (3 papers, 2021 to 2022). "Confirmation of the significance of GLUT2 in glucose reabsorption was elucidated in murine and human studies showing that the functional loss of GLUT2, either by a genetic knockout of the SLC2A2 gene in vivo or mutations in humans [Fanconi- Bickel Syndrome (FBS)], led to glucosuria (see Section 3)." (PMID 36611887, 2022).
glycogen storage disease (3 papers, 2016 to 2021). "Homozygous or compound heterozygous mutations in the SLC2A2 gene, which codes GLUT2, are believed to be responsible for a glycogen storage disease (GSD) termed GSD XI." (PMID 34948317, 2021).
Cognitive impairment (2 papers, 2020 to 2025). Abnormal cognition is characterized by deficits in thinking, reasoning, or remembering. "Additionally, an increase in SLC2A2 has been observed due astrocyte activation in AD, while a reduction in SLC1A2, particularly within the hippocampal and prefrontal cortex regions, has been noted in the advanced stages of AD and during the progression of mild cognitive impairment." (PMID 40867161, 2025).
Failure to thrive (2 papers, 2016 to 2024). Failure to thrive (FTT) refers to a child whose physical growth is substantially below the norm. "Mutations of GLUT2 (SLC2A2) are the basic defect in FBS patients with characteristic clinical features and also in patients with atypical clinical signs such as intestinal malabsorption, failure to thrive, the absence of hepatomegaly or renal hyperfiltration." (PMID 27487919, 2016).
hepatitis C (2 papers, 2017 to 2020). "In patient group who did not have hepatitis virus C infections, high SLC2A2 expression had good survival outcomes." (PMID 28978124, 2017). "However, the presence or absence of hepatitis C infection affected the significance of SLC2A2." (PMID 28978124, 2017).
lymphoma (2 papers, 2015 to 2017). A malignant (clonal) proliferation of B- lymphocytes or T- lymphocytes which involves the lymph nodes, bone marrow and/or extranodal sites. "Altered expressions of SLC2A family members have been reported in many types of cancer (liver- SLC2A1, SLC2A2, SLC2A5; pancreas- SLC2A1; breast- SLC2A1, SLC2A2, SLC2A4; stomach- SLC2A2, SLC2A4, SLC2A5, SLC2A14; lymphoma- SLC2A5)." (PMID 28978124, 2017).
MODY (2 papers, 2022). "Specifically, SLC2A2 (GLUT2), and IAPP genes were commonly enriched in MODY, while HLA-DRB4 and HLA-DRB5 genes were underlying the enrichment with T1D." (PMID 35788821, 2022).
renal cell carcinoma (2 papers, 2017 to 2021). "Furthermore, an imaging technique based on SLC2A2 could also be useful in renal cell carcinoma because SLC2A2 is mainly expressed in liver, absorptive renal cells, and pancreatic β cells." (PMID 28978124, 2017).
Anxiety (1 paper, 2020). Intense feelings of nervousness, tension, or panic often arise in response to interpersonal stresses. "Cognitive tests to assess recognition memory, spatial working memory and anxiety were performed in Slc2a2 whole-body heterozygous mice (i.e. reduced Glut2 mRNA and protein), alongside littermates expressing normal levels of the transporter." (PMID 32938474, 2020).
CADASIL (1 paper, 2020). "To shed light on the mechanism of previously observed lower FDG-PET value in the CADASIL subjects, we investigated gene expression levels of GLUT isoforms [SLC2A2 (GLUT2), SLC2A3 (GLUT3), and SLC2A4 (GLUT4)] in VSMC models of CADASIL and control subjects." (PMID 33101365, 2020).
dental caries (1 paper, 2021). The decay of a tooth, in which it becomes softened, discolored, and/or porous. "In a small study investigating multiple genotypes, allelic variation in sweet taste genes, including GNAT3, SLC2A2, SLC2A4, TAS1R1 and TAS1R2 was associated with dental caries." (PMID 34715836, 2021).
dyslipidaemia (1 paper, 2023). "In the discordant profile, the variant SLC2A2 conveys protection against T2D risk despite being associated with heavier weight and higher blood pressure, and worse liver function and dyslipidaemia." (PMID 36703017, 2023).
epilepsy (1 paper, 2016). A brain disorder characterized by episodes of abnormally increased neuronal discharge resulting in transient episodes of sensory or motor neurological dysfunction, or psychic dysfunction. "The larger CACNA1G p-value (6.56 × 10−5) when compared to hsa04930 p-value (1.2 × 10−6) suggests that the other two genes CACNA1A and/or SLC2A2 may contribute to epilepsy with small effect sizes." (PMID 27984588, 2016). "Further analysis conducted on ATP1A2, SLC2A1, SLC2A2 KCNMA1 and KCNN3 showed they all are related to epilepsy or seizures." (PMID 27984588, 2016).
gout (1 paper, 2025). A condition characterized by painful swelling of the joints, which is caused by deposition of urate crystals. "We have recently identified significant signals associated with gout located on solute carrier 2A2 (SLC2A2), which is consistent with the results of another large-scale study showing an association between SLC2A2 and serum urate; the details are to be mentioned in a later section." (PMID 40209957, 2025).
Hepatitis B infection (1 paper, 2017). "Hepatitis B infection did not affect the prognostic significance of SLC2A2." (PMID 28978124, 2017).
nephrogenic diabetes insipidus type 1 (1 paper, 2025). "Variants were additionally found in genes linked to nephrogenic diabetes insipidus type 1 (AVPR2), the SLC2A2 gene encoding the GLUT2 protein, which plays a key role in glucose metabolism, and the MAPK8IP1 gene encoding a regulator of pancreatic beta-cell function." (PMID 40149731, 2025).